CRP (C-reactive protein)
Diseases named in the same sentence as CRP in open-access papers (continued):
Sharing a sentence is not in itself a finding about the gene and the disease.
Nephropathy (continued). "Our data indicated that the level of IGFBP2 can better reflect timely the renal injury than traditional serum biomarkers (BUN, CRP, Cys-C, and SCr), indicating that IGFBP2 exhibits a good sensitivity for kidney damage." (PMID 30564296, 2018). "In our study, neutrophils and CRP of T2D patients with nephropathy were higher than those without nephropathy, while haemoglobin in T2D patients with nephropathy was lower than that in those without nephropathy." (PMID 34997893, 2021). "Nearly half (41%) of the HFRS patients fulfilled the criteria for SPS, and the levels of CRP, a marker of inflammation, were increased; however, these patients did not have increased kidney damage marker levels." (PMID 32824680, 2020). "In addition, sex, urine red blood cells, and CRP had no predictive value for survival and nephropathy outcomes in patients with ANCA-GN." (PMID 38952509, 2024). "We had shown for the first time that diabetic patients with Gilbert syndrome have a lower prevalence of vascular complications including nephropathy than those without it, in parallel with lower levels of 8-hydroxy-2’-deoxyguanosine (8-OHdG), oxidative stress marker, and high sensitivity-CRP." (PMID 35819962, 2022).
Kawasaki disease (66 papers, 2013 to 2025). A rare inflammatory disease characterized by an acute febrile, systemic, self-limiting, medium-vessel vasculitis primarily affecting children. "In summary, this study has found that the incidence of CAL in children with Kawasaki disease is 18.38%, and being male, aged ≤2 years, duration of fever ≥10 days, Hb ≤105 g/L, and CRP ≥100 mg/L are the risk factors of CAL in children with Kawasaki disease." (PMID 38711795, 2024). "Elevated ESR and CRP levels are an important marker for the acute stage of Kawasaki disease (KD), and a polymorphism in ITPR3, whose protein product mediates the release of intracellular calcium, was associated with increased serum CRP levels in KD patients." (PMID 37238156, 2023). "In the literature, serum CRP levels were found as a risk factor for the development of coronary artery dilatations and aneurysms in Kawasaki disease." (PMID 38031949, 2023). "LASSO identified haemoglobin, percentage of neutrophils, C-reactive protein level, platelet count, serum albumin, serum sodium, serum alkaline phosphatase, coronary artery damage, and complete Kawasaki disease as risk factors for IVIG resistance." (PMID 35099338, 2022). "LASSO regression reidentified haemoglobin level, percentage of neutrophils, C-reactive protein, serum albumin, and serum alkaline phosphatase levels, and complete Kawasaki disease as risk factors for IVIG resistance." (PMID 35099338, 2022). "Male sex, older, higher platelet count, higher CRP level, and lower albumin level in the initial phase of Kawasaki disease were strong risk factors of cardiac lesions." (PMID 25716055, 2015). "Clinicians should consider sex, age, platelet count, albumin levels, and CRP levels when assessing risk of cardiac lesions in the initial phase of Kawasaki disease." (PMID 25716055, 2015). "Clinicians should consider male sex, older age, higher platelet count, lower albumin levels, and higher CRP levels when assessing risk of cardiac lesions in the initial phase of Kawasaki disease." (PMID 25716055, 2015). "Extremes of age, longer duration of fever, higher white blood cell count, lower or higher platelet count, higher C-reactive protein, low hematocrit, and low serum albumin have been reported to be associated with coronary artery involvement in Kawasaki disease." (PMID 26835677, 2013). "The results of this retrospective cohort have found that the incidence of CAL in children with Kawasaki disease is 18.38%, and being male, aged ≤2 years, a duration of fever ≥10 days, Hb ≤105 g/L, and CRP ≥100 mg/L are the risk factors of CAL in children with Kawasaki disease." (PMID 38711795, 2024). "In a retrospective case–control study of 38 children with Kawasaki disease and 44 febrile controls, we measured hematological parameters and C-reactive protein (CRP) using standardized analyzers and profiled seven serum microRNAs by qRT-PCR." (PMID 41169895, 2025). "CRP and three microRNAs (miR-223-3p, miR-19a-3p, miR-18a-5p) were significantly elevated in Kawasaki disease." (PMID 41169895, 2025). "these variables were haemoglobin, percentage of neutrophils, platelet count, CRP, serum albumin, serum sodium, serum alkaline phosphatase, coronary artery damage, and incomplete Kawasaki disease." (PMID 35099338, 2022). "In the future, large sample and long follow-up studies are needed to verify the role of MMP-9, PLTs, ESR, and CRP levels in Kawasaki disease with cardiovascular injury." (PMID 36159562, 2022). "Due to similarities in presentation between MIS-C and Kawasaki disease in patients, a recent study has examined and compared the levels of serum nitrogen terminal pro-brain natriuretic peptide (NT-proBNP) and C-reactive protein (CRP) between these patients." (PMID 36297092, 2022). "This study aimed to assess the occurrence of coronary artery lesions (CAL) in patients with Kawasaki disease (KD) according to serum C-reactive protein (CRP) levels." (PMID 34078404, 2021).
Kawasaki disease (continued). "In patients with fever lasting more than five days and two or three classic symptoms of Kawasaki disease, CRP and ESR should be measured." (PMID 26859297, 2016). "Therefore, the timely detection of Hb and CRP levels is of great significance to evaluate CALs in children with Kawasaki disease." (PMID 38711795, 2024). "Spearman’s correlation analysis showed that gender (r = 0.504, p = 0.012), age (r = 0.611, p = 0.009), duration of fever ≥10 days (r = 0.579, p = 0.005), Hb (r = 0.623, p = 0.031), and CRP (r = 0.558, p = 0.018) were associated with the CAL in children with Kawasaki disease." (PMID 38711795, 2024). "Pearson’s correlation analysis showed that gender (r = 0.504), age (r = 0.611), duration of fever ≥10 days (r = 0.579), hemoglobin (Hb) (r = 0.623), and C-reactive protein (CRP) (r = 0.558) were all correlated with the CAL in children with Kawasaki disease (all p < 0.05)." (PMID 38711795, 2024). "NT-proBNP, N-terminal probrain natriuretic peptide; PT, prothrombin; PTT, partial thromboplastin time; KD, Kawasaki disease; CRP, C-reactive protein; ESR, erythrocyte sedimentation rate; IL, interleukin; LDH, lactate dehydrogenase; RT-PCR, reverse transcription-polymerase chain reaction." (PMID 36361640, 2022). "At the age of 18 months, she developed atypical Kawasaki syndrome with elevated C-reactive protein (155 mg/L; Ref: <4 mg/L), and as complications, right coronary artery dilatation (2.2 mm diameter), left coronary artery aneurysm (2.7 mm diameter) and pericardiac effusion developed." (PMID 36553633, 2022). "The differential diagnosis of “Athletes’ arteries” from normal, Kawasaki disease and multisystemic inflammation syndrome must be made carefully by performing a clinical work-up including specific blood sample sets (c-reactive protein, blood sedimentation rate, etc.)as recommended." (PMID 34821694, 2021). "We found suggestive evidence that the rate of decline in the C-reactive protein level in response to immunomodulators may have differed between younger children who met the AHA criteria for Kawasaki’s disease and other children with suspected MIS-C." (PMID 34133854, 2021). "Among the children who received IVIG alone, the smoothed curves showed rates of decline in C-reactive protein levels among those younger than 6 years of age who met the AHA criteria for Kawasaki’s disease that were similar to the rates among the remaining children." (PMID 34133854, 2021). "Besides, it turns out that the KD group patients are prone to have high CRP levels and platelet count at initial diagnosis, which has been reported as inflammatory biomarkers for Kawasaki disease." (PMID 31316949, 2019). "In Kawasaki disease, similarly to TAK, the inflammatory process is complex, and IL-6, IL-8, TNF-α, IFN-γ, and CRP are involved in the course of the disease." (PMID 37626704, 2023). "In the present study, low haemoglobin, low serum albumin, high percentage of neutrophils, high CRP, high AST, the presence of coronary artery lesions, and complete Kawasaki disease were predictors of IVIG resistance." (PMID 35099338, 2022). "In NFKD, the IL6, AST, CRP, ESR are in higher levels in comparison with other atypical Kawasaki disease." (PMID 36585531, 2022). "A recent study showed that the percentage of cTfh1 cells was negatively correlated with CRP, whereas the percentage of cTfh2 cells was positively correlated with both CRP and ESR in Kawasaki disease." (PMID 33230950, 2020). "Most previous studies indicated that the inflammatory indexes such as WBC, CRP and ESR were increased, and Hb, Plt, Hct were also changed in Kawasaki disease." (PMID 26337791, 2015).
Kawasaki disease (continued). "There are no pathognomonic laboratory tests for Kawasaki disease; however, in most cases, C-reactive protein (CRP) ≥ 3.0 mg/dL and/or erythrocyte sedimentation rate (ESR) ≥ 40 mm/h are present." (PMID 39518520, 2024). "Moreover, in multiple logistic regression analysis, CRP levels, neutrophil count, and WBC count can be used as predictors for the development of coronary artery abnormalities in Kawasaki disease." (PMID 38031949, 2023). "RBC, HB, CK, CK-MB, ALB, A/G, LC3II, ATG16L1 were positively correlated with BECN1; the incidence of IVIG-resistant Kawasaki disease, length of stay, lymph node enlargement, perianal desquamation, CAL, IL-4, IL-6, CRP, PCT, SF, CD3 + CD4 + T, and r-GT were negatively correlated with BECN1." (PMID 38114939, 2023). "However, the lack of correlation between CRP levels and the flavone and flavonol biosynthesis pathway indicating that this pathway is not the sole driver of systemic inflammation in Kawasaki disease." (PMID 40448518, 2025). "However, among the children who received glucocorticoids with or without IVIG, there was a more rapid decline in the C-reactive protein level in the group of children who did not meet the AHA criteria for Kawasaki’s disease or were over 6 years of age." (PMID 34133854, 2021). "Also, elevations of urine meprin A or filamin C in patients suspected of Kawasaki disease do not appear to correlate to acute phase reactants such as ESR or CRP." (PMID 23281308, 2013). "In addition, the cohort in our study may have included non-infectious cases characterized by high CRP levels and low mortality (e.g., Kawasaki disease, etc.)." (PMID 39015209, 2024). "When the duration of illness exceeds 8.5 days, even in the absence of typical Kawasaki disease manifestations, we should still consider the combined use of IVIG and aspirin for treatment, especially when PLT exceeds 453, CRP exceeds 156.42, or TBIL is greater than 5.95." (PMID 40144928, 2025).
enthesitis (65 papers, 2011 to 2026). Inflammation at the site of insertion of ligaments, tendons, and other fibrous structures into bone. "It was shown that the immature neutrophil score was elevated in PsA patients compared to controls and significantly correlated with disease activity based on clinical parameters (ASDAS, SPARCC, PASI, ESR, CRP, enthesitis, dactylitis)." (PMID 38802975, 2024). "Additional assessments such as pain VAS, ptGA and phGA, the presence of enthesitis and CRP also showed similar improvements." (PMID 37250652, 2023). "The study shows that secukinumab provides a rapid and sustained effectiveness up to 24 months of treatment as demonstrated by improvements in BASDAI, pain VAS, ptGA and phGA of disease, CRP levels, and enthesitis." (PMID 37250652, 2023). "Psoriatic patients who were more likely to develop PsA had a higher prevalence of baseline enthesitis, higher C reactive protein levels, and higher PD and gray-scale synovitis scores." (PMID 35071281, 2021). "The final multivariable model analysis revealed that IBP, buttock pain, enthesitis, elevated baseline CRP levels and SIJ-MRI positivity were statistically significant associations with progression to JoAS." (PMID 34862311, 2021). "IBP, buttock pain, enthesitis, elevated baseline CRP levels and SIJ-MRI positivity in patients with juvenile-onset nr-axSpA are likely to be associated with higher risks of progression to JoAS." (PMID 34862311, 2021). "IBP, buttock pain, enthesitis, elevated baseline CRP levels and SIJ-MRI positivity in patients with the disease are associated with higher risk of progression to JoAS." (PMID 34862311, 2021). "Elevated CRP (> ULN), high disease activity [DAS28 (CRP) > 5.1], presence of enthesitis, and baseline joint erosion score ≥ 3 were all associated with statistically significant abatacept treatment benefit versus placebo." (PMID 32356115, 2020). "A majority of the disease activity parameters improved significantly after weight loss, including 68/66 tender/swollen joints count, CRP, BSA, Leeds enthesitis index, HAQ and patient VAS for global health, pain and fatigue." (PMID 30635024, 2019). "Alternating buttock pain and CRP elevation were more frequently expressed in AS group, whereas enthesitis of heel was more frequent in nrAxSpA group." (PMID 30947732, 2019). "We next examined whether the levels of pSTAT3 in Th1 or Tfh cells CD4+ T cells or in CD14+CD16- monocytes were correlated with tender joints (TJ), swollen joints (SJ), enthesitis or C reactive protein (CRP)." (PMID 35087513, 2021). "Differences observed between the two subgroups include a higher male:female ratio (3:1 for AS vs 1:1.6 for nr-axSpA), higher levels of C-reactive protein (CRP) and lower rates of peripheral manifestations such as peripheral arthritis and enthesitis in AS compared with nr-axSpA." (PMID 32607793, 2020). "After 24 months, all patients had regained some weight, but a significant improvement could still be shown in swollen/tender joints count, enthesitis, CRP and HAQ, compared to baseline." (PMID 33092646, 2020). "More recently, a report from Vastesaeger defined an algorithm in which the combination of HLA-B27 genotype, age, functional status, CRP level, the presence of enthesitis, and choice of therapy at baseline enabled good prediction of anti-TNF outcome in two large cohorts of SpA patients." (PMID 30941119, 2019). "Data on the presence of peripheral arthritis, enthesitis, CRP, secondary FM, degenerative spinal disease, NSAID use and imaging data were not available for the present study and might have influenced sub-optimal response." (PMID 31432000, 2019). "The most common missing values were CRP, ESR, Schober’s test, data on systemic glucocorticoid therapy, and presence of enthesitis." (PMID 34233730, 2021). "At 24 months the swollen/66 and tender/68 joints count, Leeds enthesitis index, CRP, HAQ, DAS28-CRP and DAPSA scores were still significantly lower compared to baseline." (PMID 33092646, 2020).
enthesitis (continued). "In TNFi-exposed patients, a significant (p < 0.05) benefit of abatacept compared with placebo was seen in most subgroups of patients with the defined PPFs at baseline: CRP > ULN, joint erosion score ≥ 3, and presence of dactylitis or enthesitis." (PMID 32356115, 2020). "Peripheral arthritis, enthesitis, BASDAI, ESR, and CRP were significantly higher in patients with HLA-B∗2704 than in those with B27-negative." (PMID 26273634, 2015). "These 5 phenotypes showed considerable variation across baseline parameters, including age, sex, BMI, PsA disease duration, C-reactive protein, mean TJC and SJC, location of tender and swollen joints, DAPSA score, dactylitis and enthesitis, psoriatic spondylitis, skin involvement, and pain." (PMID 41318485, 2025). "PASDAS scoring is based on a patient (PtGA) and physician (PhGA) global score, visual analog scale (VAS) score, tender (SJC66) and swollen (SJC68) joint counts, dactylitis, enthesitis, the physical component score of the short form 36 health survey (SF36-PCS), and C-reactive protein (CRP) level." (PMID 33917826, 2021). "In PsA, certain enthesitis-related characteristics (DIP disease), a high biologic activity (CRP), and some ill-defined genetic factors (family history) may contribute to a higher disease impact perception." (PMID 32295620, 2020). "A significant but lesser benefit of abatacept was also observed in subgroups of patients without these PPFs at baseline, i.e., those without high disease activity [DAS28 (CRP) ≤ 5.1] and with no enthesitis." (PMID 32356115, 2020). "At baseline BMI was positively correlated with several measures of disease activity and function including DAS28CRP, DAPSA, tender joints count, CRP, patient’s global health VAS, Leeds enthesitis index and HAQ (Spearman’s rho ranged from rS = 0.312, p = 0.047 to rS = 0.483, p = 0.001)." (PMID 30635024, 2019). "We recorded at baseline and every 6–8 weeks over the 12-month period the age, gender, disease duration, peripheral arthritis or enthesitis, HLA-B27 status, BASDAI, CRP, ESR, BASFI, and three visual analogue scales, spine global pain, spinal night time pain, and patient’s global assessment." (PMID 30953541, 2019). "As previously discussed, the utility of DAS28–3(CRP) is limited because of the small number of components included in the composite and the lack of inclusion of measures of skin disease, enthesitis, dactylitis, or PROs." (PMID 30373651, 2018). "These are the DAPSA index, which includes the number of swollen and tender joints, CRP, visual analogue scale for pain as well as disease activity assessment, and PASDAS, which similarly to sMDA, includes peripheral joint, but also skin, and enthesitis domains." (PMID 38522049, 2024). "In our analysis, patient-perceived impact, physician global assessment, SJC and skin disease were higher in lower GDP/capita countries whereas enthesitis and CRP were not, with the highest differences observed for PROs and physician global assessment, as evidenced by effect sizes." (PMID 35523519, 2022). "Bone marrow edema and enthesitis can both be explained by increased mechanical stress (consideration of alternative diagnoses) and if the patient is HLA-B27 negative, has normal CRP and no structural imaging findings (consideration of negative test results), then SpA would be highly unlikely." (PMID 35199195, 2022). "A negative correlation was also observed between enthesitis score, CRP, and ESR for SF-36." (PMID 30700326, 2019). "Risk factors for structural damage progression that may be screened for and monitored include serum C-reactive protein (CRP); dactylitis count; enthesitis (yes/no),\; PsA subtype and duration; and numbers of joint erosions, joints with joint space narrowing (JSN), and swollen joints." (PMID 36627711, 2023).
enthesitis (continued). "In perSpA patients, there were significant negative correlations identified between CRP (r=-0.77, p<0.0001), ASDAS (r=-0.81, p=0.0014) and the presence of enthesitis (r=-0.62, p=0.0193) and the expression levels of miR-487b." (PMID 37138886, 2023). "The ASDAS, which includes CRP level and three questions (spinal pain, peripheral joint pain and morning stiffness duration) from the BASDAI but does not include assessment of enthesitis and assigns less weight to peripheral disease activity, is believed by some to be more objective than the BASDAI." (PMID 38765190, 2024).